VPS16 (VPS16 core subunit of CORVET and HOPS complexes)
Description:
Plays a role in vesicle-mediated protein trafficking to lysosomal compartments including the endocytic membrane transport and autophagic pathways. Believed to act as a core component of the putative HOPS and CORVET endosomal tethering complexes which are proposed to be involved in the Rab5-to-Rab7 endosome conversion probably implicating MON1A/B, and via binding SNAREs and SNARE complexes to mediate tethering and docking events during SNARE-mediated membrane fusion. The HOPS complex is proposed to be recruited to Rab7 on the late endosomal membrane and to regulate late endocytic, phagocytic and autophagic traffic towards lysosomes. The CORVET complex is proposed to function as a Rab5 effector to mediate early endosome fusion probably in specific endosome subpopulations. Required for recruitment of VPS33A to the HOPS complex. Required for fusion of endosomes and autophagosomes with lysosomes; the function is dependent on its association with VPS33A but not VPS33B. The function in autophagosome-lysosome fusion implicates STX17 but not UVRAG.
Synonyms: hVPS16; DYT30
Tractability: Small molecule: a structure with a bound ligand is known. Antibody: UniProt places it where antibodies can reach, with high confidence. PROTAC: ubiquitination databases record sites on it; its protein half-life has been measured.
Gene: Protein-coding gene on chromosome 20 (2,840,689 to 2,866,800, forward strand). Ensembl gene ENSG00000215305.
Subcellular location: Late endosome membrane; Lysosome membrane; Early endosome; Cytoplasmic vesicle, clathrin-coated vesicle; Cytoplasmic vesicle, autophagosome
Pathways (Reactome):
Disease: SARS-CoV-2 modulates autophagy
Gene Ontology:
Molecular function: molecular adaptor activity; protein binding; actin binding; actin filament binding
Biological process: autophagosome maturation; autophagosome-lysosome fusion; endosome to lysosome transport; endosomal transport; endosomal vesicle fusion; regulation of SNARE complex assembly; vacuole fusion, non-autophagic; intracellular protein transport; vacuole organization
Cellular component: early endosome; HOPS complex; late endosome; lysosomal membrane; lysosome; recycling endosome; CORVET complex; endosome membrane; autophagosome; axon; clathrin-coated vesicle; cytoplasm; endosome; late endosome membrane; neuronal cell body; presynapse; vesicle tethering complex
Genetic constraint (gnomAD): Loss-of-function variants: 82 observed, 121.12 expected, observed/expected ratio (o/e) 0.68, 90% interval 0.56 to 0.81. The upper end of that interval is the gene's LOEUF score, 0.81, which puts it in group 3 of 6, group 1 being the genes least tolerant of losing a copy. Missense variants: 928 observed, 1,143.5 expected, observed/expected ratio (o/e) 0.81, 90% interval 0.77 to 0.86. Synonymous variants: 406 observed, 444.6 expected, observed/expected ratio (o/e) 0.91, 90% interval 0.84 to 0.99.
Homologues: Orthologues: chimpanzee VPS16 (99% identical), macaque VPS16 (98% identical), rabbit VPS16 (98% identical), guinea pig VPS16 (97% identical), mouse Vps16 (97% identical), rat Vps16 (97% identical), dog VPS16 (95% identical), pig VPS16 (93% identical), zebrafish vps16 (67% identical), tropical clawed frog vps16 (67% identical), Drosophila melanogaster Vps16A (36% identical), Caenorhabditis elegans vps-16 (25% identical).
Diseases named in the same sentence as VPS16 in open-access papers:
VPS16 is named in the same sentence as 33 diseases in open-access papers, as found by Europe PMC text mining. Sharing a sentence is not in itself a finding about the gene and the disease. The quoted sentences say what the papers report.
Dystonia (15 papers, 2016 to 2025). An abnormally increased muscular tone that causes fixed abnormal postures. "Our study showed geographically diverse differences in the phenotypic presentation of VPS16-associated dystonia as myoclonus, intellectual disability, and psychiatric symptoms were more common in the European cohort." (PMID 40655316, 2025). "The study aimed to describe the clinical, imaging, and genetic profile of patients with VPS16-associated dystonia from India and compare the findings with the Chinese and European cohorts." (PMID 40655316, 2025). "In our study, there were few differences in the phenotypic presentation of VPS16-associated dystonia across geographical regions, but the European cohort had a higher prevalence of myoclonus, intellectual disability, and psychiatric symptoms." (PMID 40655316, 2025). "The study aims to provide a description of the clinical, imaging, and genetic profiles of patients with VPS16-associated dystonia and to compare the findings of Indian cohort with that of Chinese and European cohorts." (PMID 40655316, 2025). "Monoallelic variants in VPS16 are associated with early-onset dystonia (VPS16-associated dystonia) with a frequency of less than 4%." (PMID 40655316, 2025). "The frequency of VPS16-associated dystonia is estimated to be between 0.9 and 4% of genetic dystonias." (PMID 40655316, 2025). "Variants in the genes encoding for the HOPS complex have been associated with the etiopathogenesis of inherited dystonia (i.e., VPS16, VPS41, and VPS11)." (PMID 40655316, 2025). "Description of the clinical, imaging, and genetic profile of VPS16-associated dystonia and comparison of the findings of the Indian cohort with that of the Chinese and European cohorts." (PMID 40655316, 2025). "VPS16-associated dystonia can be inherited either as an autosomal dominant pattern with incomplete penetrance or recessive inheritance." (PMID 40655316, 2025). "VPS-16 associated dystonia have primarily been reported from Europe and China, but the reports from the Indian continent are lacking." (PMID 40655316, 2025). "Heterozygous VPS16 loss‐of‐function mutations thus appear to have reduced penetrance and can possibly be viewed as a genetic risk factor for dystonia." (PMID 33938619, 2021). "Vps16 mutant mice exhibited significantly impaired motor function, suggesting that VPS16 is a new causative gene of dystonia." (PMID 27174565, 2016). "VPS16-associated dystonia is a new genetically mediated dystonic syndrome." (PMID 40655316, 2025). "Two cases of VPS16-associated dystonia have been previously published by our institute." (PMID 40655316, 2025). "We had 1 patient with VPS16-associated dystonia available for assessment in our cohort." (PMID 40655316, 2025). "VPS16-associated dystonia (OMIM ID: 619291) is associated with monoallelic variants in VPS16 gene." (PMID 40655316, 2025). "We aimed to study the ethnic phenotypic and genotypic differences of VPS16-associated dystonia." (PMID 40655316, 2025). "Dystonia is associated with mutation in the VPS16 gene, previously known as Dystonia 30 (DYT30), in a childhood-onset dystonia characterized by prominent oromandibular, cervical, bulbar, or upper limb dystonia, followed by slow progression to generalized dystonia." (PMID 35207493, 2022). "To examine whether VPS16 was associated with dystonia in additional patients, we performed Sanger sequencing of the entire VPS16 exons in 14 unrelated sporadic cases with adolescent-onset dystonia compatible with autosomal recessive inheritance." (PMID 27174565, 2016). "Report of a single patient with VPS16-associated dystonia and review of reported cases of genetically confirmed DYT-VPS16 since 2016 from Indian, Chinese and European cohorts." (PMID 40655316, 2025). "The most frequently implicated genes included the well‐established isolated and combined dystonia genes VPS16 (n = 17 index patients), THAP1 (n = 14), GCH1 (n = 13), SGCE (n = 12), GNAL (n = 8), and KMT2B (n = 8)." (PMID 40533913, 2025).
Dystonia (continued). "Forty-five PD individuals (0.57%) carried 26 distinct (likely) pathogenic variants in nine dystonia-linked genes, most frequently in GCH1, followed by VPS16." (PMID 40672488, 2025). "The frequencies of these genetic forms in our dystonia sample were 0.9% (17/1895 index patients) for VPS16, 0.3% (5/1895) for EIF2AK2, and 0.05% (1/1895) for EIF4A2." (PMID 40533913, 2025). "The clinical phenotype of VPS16-related dystonia (OMIM#619291) is characterized by early-onset isolated dystonia, predominantly affecting the oromandibular, bulbar, cervical, and upper limb regions, followed by slow progressive generalization, typically preserving ambulation into adulthood." (PMID 40724495, 2025). "The majority (n=43) were carriers of heterozygous variants in genes linked to dominantly inherited dystonia genes (ATP1A3, GCH1, SGCE, KMT2B, THAP1, TOR1A, and VPS16), while only one carrier of a homozygous PLA2G6 variant and one of compound-heterozygous PTS variants were identified." (PMID 40672488, 2025). "Recent discoveries have expanded the genetic landscape of dystonia, identifying novel contributors such as AOPEP, VPS11, VPS16, and EIF2AK2." (PMID 40584247, 2025). "Of these, the genes VPS16, EIF2AK2, and EIF4A2, which were relatively recently associated with dystonia, were not included in the prescreening process." (PMID 40533913, 2025). "In accordance with the scientific literature, we detected potentially relevant variations in known genes previously associated with CD and BSP, such as CIZ1, GNAL, and ANO3, and in other dystonia-related genes, such as KMT2B, VPS16, and KCNN2, for a total of nine patients." (PMID 37445923, 2023). "Notably, 43 out of 84 variants (51.2%) in established dystonia genes were not previously reported, including two novel recurrent variants (EIF2AK2:p.Pro31Ser and VPS16:p.Ile484Thrfs*70)." (PMID 40533913, 2025).
Brain atrophy (2 papers, 2021 to 2022). Partial or complete wasting (loss) of brain tissue that was once present. "Here, we report a new disease caused by a bi‐allelic intronic variant in VPS16, characterized by severe developmental regression, delayed myelination, brain atrophy with thin corpus callosum, coarse facial features, hypertrichosis, dysostosis multiplex, neutropenia, and feeding difficulties." (PMID 33938619, 2021). "Patients with bi‐allelic variants in VPS16 showed a more severe phenotype with similar features to PI4K deficiency, including delayed myelination, brain atrophy, neutropenia, skeletal abnormalities, and dysmorphic features." (PMID 35880319, 2022).
focal dystonia (2 papers, 2023 to 2024). A dystonia that is localized to a specific part of the body. "However, VPS16 variants have recently been detected in patients with focal dystonia." (PMID 37445923, 2023). "Our findings further suggest that VPS16 variants may be considered in cases of focal dystonia." (PMID 37445923, 2023). "Nevertheless, VPS16 variations have recently been discovered among patients suffering from focal dystonia." (PMID 38612382, 2024). "Furthermore, these results imply that VPS16 variations should be evaluated in cases of focal dystonia." (PMID 38612382, 2024).
Cognitive impairment (1 paper, 2024). Abnormal cognition is characterized by deficits in thinking, reasoning, or remembering. "Together, these data demonstrate that zebrafish vps16(-/-) mutants show systemic defects, neurological and motor system pathologies, and cognitive impairment." (PMID 39000367, 2024).
Fanconi anemia (1 paper, 2023). Fanconi anemia (FA) is a hereditary DNA repair disorder characterized by progressive pancytopenia with bone marrow failure, variable congenital malformations and predisposition to develop hematological or solid tumors. "The signaling pathways involved in VPS16 include neuroactive ligand-receptor interaction, cell cycle, primary immunodeficiency, Fanconi anemia pathway, and nicotine addiction." (PMID 37124933, 2023).
generalized dystonia (1 paper, 2025). "VPS16 is associated with early-onset generalized dystonia, often accompanied by mild neurodevelopmental features." (PMID 40584247, 2025).
liver cancer (1 paper, 2023). An epithelial or non-epithelial malignant neoplasm that arises from the liver. "The clinical characteristics and VPS16 H-score of 12 cases of liver cancer and 3 cases of normal hepatocytes in the HPA database were analyzed." (PMID 37124933, 2023).
malaria (1 paper, 2025). Malaria is a serious and sometimes fatal disease caused by a parasite that commonly infects a certain type of mosquito which feeds on humans. "For VPS16, disruption of correct trafficking of luminal rhoptry and microneme proteins to their respective organelles, and subsequent inability for the malaria merozoite to invade its next RBC, was the dominant phenotype independent of the time of induction." (PMID 40198740, 2025).
mucopolysaccharidosis (1 paper, 2022). A group of autosomal recessive or X-linked inherited lysosomal storage disorders affecting the metabolism of mucopolysaccharides, resulting in the accumulation of mucopolysaccharides in the body. "Genetic deficiency of the HOPS/CORVET subunit VPS16 has been found to phenocopy mucopolysaccharidosis plus disease." (PMID 36153662, 2022). "Of note, two patients have been lately reported with an overlapping phenocopy of mucopolysaccharidosis plus disease caused by genetic deficiency of VPS16, another subunit of the HOPS and CORVET tethering complexes to which VPS33A is recruited by binding." (PMID 36153662, 2022).
mucopolysaccharidosis-plus syndrome (1 paper, 2024). "Towards this end, mutations in the human gene Vacuolar Protein Sorting 16 (VPS16) have recently been associated with a novel type of MPS named Mucopolysaccharidosis-Plus Syndrome (MPS-PS)." (PMID 39000367, 2024).
parasitemia (1 paper, 2025). "To analyse the importance of the VPS11, VPS16 and VPS18 HOPS/CORVET core subunits for blood stage development, we monitored the parasitemia of synchronised cultures grown without (control) or in presence of rapalog over two replication cycles (4 days) using flow cytometry." (PMID 40198740, 2025).
tumor (2 papers, 2023). "In this study, we analyzed the expression of VPS16 in tumor tissues and normal tissues by LIHC using the TCGA database." (PMID 37124933, 2023). "To verify the expression of VPS16 in LIHC, we analyzed the mRNA levels of 374 LIHC tumor samples and 50 normal samples in TCGA and found that VPS16 was highly expressed in LIHC." (PMID 37124933, 2023). "This also further validated that VPS16 was differentially expressed in LIHC and normal hepatocyte tissues and has the potential as a tumor marker in the future." (PMID 37124933, 2023).
cancer (1 paper, 2023). A tumor composed of atypical neoplastic, often pleomorphic cells that invade other tissues. "Some recent studies have shown that the VPS-C protein is a promising target for cancer therapy, suggesting that VPS16 and related genes may have similar effects." (PMID 37124933, 2023). "Vacuolar protein sorting 16 (VPS16) overexpression was recently considered related to cancer growth and drug resistance; however, little is known about whether VPS16 plays a vital role in liver hepatocellular carcinoma (LIHC)." (PMID 37124933, 2023). "The results showed that the upregulated genes in the high-expression group of VPS16 were mainly concentrated in the mitotic cell cycle and DNA replication pathways, suggesting that VPS16 may play a role in promoting cancer by affecting the cell cycle and mitosis." (PMID 37124933, 2023).
neurological disorders (1 paper, 2024). "Mutations in core proteins (VPS11, VPS16, VPS18, and VPS33) have been linked with multiple neurological disorders, including mucopolysaccharidosis (MPS), genetic leukoencephalopathy (gLE), and dystonia." (PMID 39000367, 2024).
VPS16 also shares sentences with these, for which no sentence is quoted: movement disorder (3 papers); neutropenia (2); Parkinson disease (2); Ataxia (1); dysostosis multiplex (1); Gaucher disease (1); hepatocellular carcinoma (1); Hermansky-Pudlak syndrome (1); hypertrichosis (1); idiopathic dystonia (1); Intellectual disability (1); Krabbe disease (1); lysosomal storage disease (1); Myoclonus (1); nicotine addiction (1); ovarian carcinoma (1); Parkinsonism (1); primary immunodeficiency (1); Zika virus infection (1).